ZNF100 (zinc finger protein 100)
Description:
May be involved in transcriptional regulation.
Tractability: PROTAC: ubiquitination databases record sites on it.
Gene: Protein-coding gene on chromosome 19 (21,722,771 to 21,767,598, reverse strand). Ensembl gene ENSG00000197020.
Subcellular location: Nucleus
Pathways (Reactome):
Gene expression (Transcription): Generic Transcription Pathway
Gene Ontology:
Molecular function: protein binding; DNA-binding transcription factor activity, RNA polymerase II-specific; RNA polymerase II cis-regulatory region sequence-specific DNA binding
Biological process: regulation of DNA-templated transcription; regulation of transcription by RNA polymerase II
Cellular component: nucleus
Genetic constraint (gnomAD): Loss-of-function variants: 15 observed, 17.48 expected, observed/expected ratio (o/e) 0.86, 90% interval 0.57 to 1.32. The upper end of that interval is the gene's LOEUF score, 1.32, which puts it in group 5 of 6, group 1 being the genes least tolerant of losing a copy. Missense variants: 670 observed, 643.49 expected, observed/expected ratio (o/e) 1.04, 90% interval 0.98 to 1.11. Synonymous variants: 226 observed, 213.24 expected, observed/expected ratio (o/e) 1.06, 90% interval 0.95 to 1.18.
Homologues: Paralogues in human: ZNF431 (58% identical), ZNF430 (58% identical), ZNF92 (49% identical), ZNF257 (48% identical), ZNF680 (48% identical), ZNF737 (47% identical), ZNF98 (47% identical), ZNF723 (46% identical), ZNF66 (46% identical), ZNF730 (45% identical), ZNF273 (44% identical), ZNF675 (44% identical), and 6 more.
Diseases named in the same sentence as ZNF100 in open-access papers:
ZNF100 is named in the same sentence as 8 diseases in open-access papers, as found by Europe PMC text mining. Sharing a sentence is not in itself a finding about the gene and the disease. The quoted sentences say what the papers report.
colorectal cancer (1 paper, 2017). A primary or metastatic malignant neoplasm that affects the colon or rectum. "ZNF100 is among the 30 most hypermethylated genes in colorectal cancer and is frequently mutated in multiple myeloma with mutated alleles preferentially expressed." (PMID 29029385, 2017).
gastrointestinal stromal tumor (1 paper, 2017). "Knockdown screens have shown that ZNF100 knockdown sensitizes gastrointestinal stromal tumor cells to sunitinib and imatinib treatment." (PMID 29029385, 2017).
ovarian carcinoma (1 paper, 2017). A malignant neoplasm originating from the surface ovarian epithelium. "In a public dataset, MEF2D and ZNF100 expression were both associated with ovarian cancer progression-free or overall survival time." (PMID 29029385, 2017). "To determine if candidate variants at 19p12 interact with the ZNF100 promoter region through long-range chromatin interactions, we performed chromatin conformation capture (3C) analyses in COV362 and OVCAR8 ovarian cancer cell lines." (PMID 29029385, 2017). "The 19p12-13 region is amplified in ovarian cancer and ZNF100, and other ZNF genes, show increased expression in tumors with these amplifications." (PMID 29029385, 2017).
serous ovarian cancer (1 paper, 2017). "The Kaplan-Meier plotter (KM-plot) web-based application was used to assess associations between MEF2D and ZNF100 expression and outcome using data available from serous ovarian cancer patients." (PMID 29029385, 2017). "These cell lines were prioritized for study based on ZNF100 expression in serous ovarian cancer cell lines." (PMID 29029385, 2017).
tuberculosis (1 paper, 2024). A chronic, recurrent infection caused by the bacterium Mycobacterium tuberculosis. "The discovery of lncRNA ZNF100-6:2 and its association with active tuberculosis marks a significant advancement in our understanding of the disease and opens up new opportunities for improving TB diagnostics and patient care." (PMID 38475909, 2024). "The results showed that the expression level of lncRNA ZNF100-6:2 returned to the normal range following successful anti-tuberculosis treatment." (PMID 38475909, 2024). "In these subsequent studies, the value of lncRNA ZNF100-6:2 expression levels in neutrophils for diagnosing active tuberculosis will be further analyzed." (PMID 38475909, 2024). "Therefore, future research exploring the molecular mechanisms and functions of lncRNA ZNF100-6:2 may shed light on its role in tuberculosis pathogenesis and potentially reveal new avenues for tuberculosis diagnosis and treatment." (PMID 38475909, 2024). "Subsequent validation tests demonstrated down-regulation of lncRNA ZNF100-6:2 in patients with active PTB, which was restored following anti-tuberculosis treatment." (PMID 38475909, 2024).
cancer (2 papers, 2017 to 2025). A tumor composed of atypical neoplastic, often pleomorphic cells that invade other tissues. "ZNF100 encodes a zinc finger protein transcription factor of which little is known, although the literature indicates that this gene may have a role in cancer." (PMID 29029385, 2017).
tumor (1 paper, 2021).
ZNF100 also shares sentences with these, for which no sentence is quoted: multiple myeloma (1 paper).